TIA1 (TIA1 cytotoxic granule associated RNA binding protein)
Diseases named in the same sentence as TIA1 in open-access papers (continued):
Sharing a sentence is not in itself a finding about the gene and the disease.
tumor (continued). "T-cell intracellular antigen 1 (TIA1) is an important tumor suppressor involved in many aspects of carcinogenesis and cancer development." (PMID 28257633, 2017). "BA inhibits the cADPR Ca2+ pathway which activates cell proliferation and inhibits differentiation and activates TIA-1 which has been reported to inhibit tumor progression and invasion." (PMID 27587023, 2017). "Tumor cells were consistently positive for the cytotoxic marker TIA-1 (52/55, 94.5%), less frequently, the expression of GrB (32/45, 71.1%) and perforin (31/42, 73.8%) was noticed." (PMID 27564014, 2016). "Immunohistochemical overexpression of TIA1 ectopically localized in the cytoplasm of tumor cells was an independent prognosticator for worse overall survival in a cohort of 143 ESCC patients." (PMID 26958940, 2016). "Tumor cells also expressed cytotoxic granules, including TIA-1, granzyme B and perforin, and were often EBV positive." (PMID 26126576, 2015). "As the ectopic expression of TIAR was more efficient and reproducible than TIA1 expression to drive tumor size reduction, we tested the capacity of TIAR expression to delay the growth of nascent tumors." (PMID 25741594, 2015). "A few T-cells that coexpressed CD8 and TIA-1 (mouse mAb, clone TIA-1, 1:100, Biocare, Concord, CA, USA) antigens infiltrated the microfollicles of the neoplasm." (PMID 25810939, 2015). "Compared with tumors formed by control cells, a significant and reproducible decrease in tumor size was noted in TIA1 (four out of six (67%)) and TIAR (four out of five (80%)) cells, although tumor size was more heterogeneous from TIA1-expressing cells." (PMID 25741594, 2015). "Accordingly, the number of cells expressing caspase-3 in control tumor sections was 10% compared with 25 and 30% found in TIA1 and TIAR groups, respectively." (PMID 25741594, 2015). "Activation of TIA-1 in HeLa cells has been shown to prevent cell proliferation, tumor growth, and invasion." (PMID 25425213, 2015). "The tumor cells revealed a positive immunoreaction for cluster of differentiation (CD)3ɛ, CD56, Epstein-Barr virus (EBV)-encoded small RNAs, granzyme B and TIA1, with a Ki67 of 60–70%." (PMID 25289105, 2014). "In conclusion, these studies provide mechanistic evidence that curcumin mediated inhibition of COX-2 and VEGF expression occurs through increased expression of RNA binding proteins CUGBP2 and TIA-1 resulting in mitotic catastrophe of the tumor cells." (PMID 21347286, 2011). "Here we observed that curcumin treatment resulted in a significant increase in both CUGBP2 and TIA-1 mRNA and protein expression in the tumor xenografts." (PMID 21347286, 2011). "Immunohistochemical quantification (score 0-3) was performed for CD3, CD4, CD8, CD45RO, CD68, CD163, FoxP3, GranzymeB, iNOS, mast cell tryptase, MUM1, PD1 and TIA-1 tumor-infiltrating (TILs) reactive cells." (PMID 21179245, 2010). "DSS was positively associated with intraepithelial TIA-1+ cells (p = 0.0003), as well as expression of MHC class I and II by tumor cells (p = 0.0014 and 0.0026 respectively) (&J)." (PMID 19641607, 2009). "Similar to the results for MHC class I, the expression of MHC class II in tumor epithelium was positively associated with various T cell markers, including CD3, CD4, CD8, CD45RO, TIA-1, Granzyme B, CD25 and FoxP3." (PMID 19641607, 2009). "Similar to CD3+ cells, CD8+, CD4+, FoxP3+ and TIA-1+ cells were generally denser in tumor stroma than tumor epithelium." (PMID 18923710, 2008). "This was particularly evident for NK (CD56 and NK1) and cytotoxic markers (Granzyme B and TiA1) inside residual tumour aggregates." (PMID 16404427, 2006). "Collectively, the data suggest that TIA1 condensation may locate at the nexus of tumor metabolism and adaptive immunity." (PMID 41300366, 2025).
tumor (continued). "Conversely, enforced expression of wild-type TIA1, but not deletion of the low-complexity domain (ΔLCD), was associated with tumor growth restraint in vivo." (PMID 41300366, 2025). "It is possible that the increase in TIA1 in the xenografts derived from the miR-211 deletion lines compared to deletion-only cell lines reflects the influence of media-influenced tumour growth on the expression of tumour progression-related genes." (PMID 39594467, 2024). "Immunohistochemically neoplastic cells are typically CD3+, CD7+, CD103+, TCRβ+/− cells, CD4−, CD8−, and CD5−, mostly expressing CD30 with CD56 negativity, and demonstrate an activated cytotoxic phenotype (perforin+, granzyme B+, and TIA-1+), reflecting the origin of the tumor from cytotoxic IELs." (PMID 37627888, 2023). "In addition, these tumours are TIA1+ granzyme B+ CD103+ CD335/NKp46+ NKG2D+, and aberrant CD20 expression is common." (PMID 35626087, 2022). "Based on these results, it was hypothesized that a reduced proportion of total T cells mirrored by increased CD8+, TIA‐1+ T cells in the tumor and/or lesion might correlate with a positive response to IL‐12 therapy." (PMID 35790025, 2022). "Therefore, this study confirms the potential use of increased IFN‐γ levels posttreatment as a correlate of response to IL‐12 gene therapy and the potential importance of increased CD4+ and TIA‐1+ CD8+ T cell tumor infiltration." (PMID 35790025, 2022). "AAV8-mediated TIA1 silencing was performed at 8.5 months of age before tumor appearance." (PMID 35406476, 2022). "TIA1 and RBFOX2 were reportedly associated with tumor relapse or metastasis in malignancies." (PMID 36147313, 2022). "However, our study breaks the current view of TIA1 as a strict tumor promoter in HCC and reveals a more complex and context-dependent function." (PMID 35406476, 2022). "The tumor cells were also positive for the cytotoxic marker TIA-1." (PMID 34749754, 2021). "Patients with the tumor located at the PT had more infiltration of TIA1+ cells compared with tumors located in the DF (PT: 53.3%, N = 16; vs. DF: 24.6%, N = 15; p = 0.010) and a higher expression of p-glycoprotein (PT: 64.5%, N = 20; vs. DF: 40.3%, N = 25; p = 0.047)." (PMID 34885185, 2021). "Moreover, as is validated in previous research, TIA1 is an important tumor suppressor involved in many aspects of carcinogenesis and cancer development." (PMID 34760694, 2021). "In all seven cases, tumor cells were positive for TIA‐1 and PD‐L1 (clone SP142)." (PMID 32424876, 2020). "TIA1 is an important tumor suppressor in many cancers, especially in CRC." (PMID 28257633, 2017). "TIA1 can also function as a translational silencer of COX-2 expression in neoplasia." (PMID 28257633, 2017). "Moreover, we provided evidence that miR-19a can promote CRC cell proliferation and migration in vitro and accelerate tumor growth in vivo by targeting TIA1." (PMID 28257633, 2017). "miR-19a could promote cell proliferation and migration in CRC cells and accelerated tumor growth in xenograft mice by targeting TIA1." (PMID 28257633, 2017). "Similarly, both non-tumor and tumor tissues of primary ESCC predominantly expressed TIA1-v2 mRNA, and the TIA1 mRNA expression levels in tumors were higher than in those in paired non-tumor tissues in 3/6 (50%) of ESCC cases whose RNA was available." (PMID 26958940, 2016). "Notably, higher immunoreactivity toward Ki-67, a cell proliferation marker, was observed preferentially in tumor cells with higher cytoplasmic TIA1 immunoreactivity, suggesting that cytoplasmic TIA1 promotes the proliferation of ESCC cells." (PMID 26958940, 2016). "Tumor size was measured before and following Dox-induced expression of TIA1 or TIAR proteins." (PMID 25741594, 2015). "The tumor cells were strongly expressed CD3ε, CD56, TIA-1, granzyme B and EBV-encoded RNAs." (PMID 23773344, 2013).
tumor (continued). "Immunohistochemically, the tumor cells were cytokeratin -, vimentin +, CD3+, CD45RO+, CD5-, CD7-, CD4-, CD8-, CD10-, CD20-, CD30-, CD79a-, CD138-, CD56-, granzyme B-, TIA-1 cytotoxic granule-associated RNA binding protein (TIA-1) + and ALK-." (PMID 22931631, 2012). "Additionally, we identify a small population of CD8- but TIA-1+ tumor infiltrating cells representing populations of TCRγδ cells and neutrophils and to a lesser extent CD4+ T cells, macrophages, NK cells, and NK/T cells." (PMID 21179245, 2010). "The coherence between tumor-intrinsic metabolic phenotypes (lactate/ECAR), decreased glycolytic enzyme expression, and TIA1–mRNA association suggests that TIA1-dependent condensates are a hypothesis-generating axis rather than a validated therapeutic target at present." (PMID 41300366, 2025). "Collectively, the gain-of-function, loss-of-function, and patient-derived data all suggested that TIA1 condensates may constitute the molecular switch that couples BCG exposure to tumor cell glycolytic repression and revitalization of CD8+ T cell anti-tumor immunity." (PMID 41300366, 2025). "Finally, we identified several RBPs such as PCBP2, SNRNP70, HuR, and TIA1, which might contribute to splicing differences between different groups of neoplasm grade in BLCA." (PMID 37810965, 2023). "Furthermore, in other types of cancer, such as colorectal and gastric cancer, TIA1 mRNA has been shown to interact with miRNAs (miR-19a and miR487a, respectively), leading to a decrease in its abundance in the cell and consequent pro-tumor effects." (PMID 35163320, 2022). "Indeed, recent literature reveals that TIA1-mediated signaling captures a broad spectrum of survival and stress pathways that likely influence its contrasting antagonistic functions as proto-oncogene and tumor suppressor." (PMID 34884582, 2021). "As described in murine tumor tissues, in IL-30NegPC samples, the lack of IL-30 in both cancer and infiltrating leukocytes was associated with a scanty to absent Foxp3+Treg cell content and a distinct TIA-1+CD4+T cell infiltrate." (PMID 31366386, 2019). "We hypothesize that TIA-1 plays a fundamental role in the post-transcriptional regulation of NAP1L1 and that alteration of this regulatory process contributes to NAP1L1-associated tumor development." (PMID 24401680, 2014). "Immunohistochemical staining showed that the tumor cells were positive for CD3, CD8, CD20 (weak), CD56, and TIA-1." (PMID 41328359, 2026). "Tumor cells expressed T-cell markers (CD2, CD3, CD5, CD7; heterogeneous) and cytotoxic markers (TIA-1) and showed CD30 and CD56 positivity, with EBV positivity confirmed by EBER in situ hybridization." (PMID 41744967, 2026). "Tumor cells usually express βF1 (TCR-β), cytotoxic proteins such as TIA-1, granzyme B, and perforin, and exhibit a high Ki-67 proliferation index (>75%)." (PMID 41227238, 2025). "Laparotomy revealed a transmural tumor mass, and histopathological and immunohistochemical analyses confirmed EATL (CD3+/CD103+/TIA-1+/GRANB+, CD5-/CD8-, Ki-67 ~70%)." (PMID 41357592, 2025). "Together with the bulk TIMER plots, these data converge on the conclusion that TIA1-rich tumor islands recruit and activate CD8+ T cells, and that condensate-competent TIA1 within cancer cells is required to sustain this immunogenic dialog." (PMID 41300366, 2025). "When TIA1 was silenced, BCG lost its efficacy: Sh-mTia1 tumors retained intense photon flux, persistent tumor architecture, high LDHA/HK2/PKM2 levels, and unaltered lactate output." (PMID 41300366, 2025). "Tumor cells in MEITL are typically CD3+, CD5−, CD7+, CD4−, TIA-1+, granzyme B+, perforin+, and CD103+." (PMID 39447336, 2024). "Aiming to discover further potential treatment approaches, we investigated the role of MR3 expression in the CRC tumor immune microenvironment by immunohistochemical analysis for a selection of promising immunomarkers: CD8, FOXP3, IL17, TIA-1, CD16 and OX40." (PMID 37175905, 2023).
tumor (continued). "B7-H4 was mainly expressed on tumor cells, whereas there was a diversity in the expression pattern of CD8 and TIA-1 in individual cases." (PMID 34275008, 2022). "Knockdown of TIA-1 increased tumor growth and invasion in mice, while TIA-1 expression is down-regulated in a variety of human tumor tissues." (PMID 36231015, 2022). "In this regard, our data support a tumor-suppressive role for TIA1 in HCC initiation, but likely a tumor-promoting function in cancer cells after transformation." (PMID 35406476, 2022). "The activity of direct cofactors of TIA1 can also be deeply involved in HCC development as recently reported for TIAR, which in line with our data, has a tumor-suppressive role in HCC." (PMID 35406476, 2022). "In keeping with NK-cell origin in many cases, the tumour stains positive for CD2, CD3ε, CD7, CD56, cytotoxic granules (TIA1, granzyme, perforin), CD158/KIR and CD335/NKp46 but is usually negative for sCD3, CD4, CD8, CD57 and TCR." (PMID 35626087, 2022). "A large number of lymphocytes with CD8+ and TIA-1+ and cytotoxic T cells were detected, and plasma cell infiltration occurred in the stroma around the PPLELC tumor cells." (PMID 34760925, 2021). "Our data showed infiltration of T (CD3+), CD8 T (CD8+) and B cells (CD20+) in more than 50% of the tumor samples and a lower infiltration of CD4 T cells (CD4+) and CL (TIA1+)." (PMID 34885185, 2021). "Immunohistochemistry (IHC) highlighted tumor cells as strongly positive for CD3, CD56, CD5, CD2, CD8, CD4, CD43, T-cell restricted intracellular antigen 1 (TIA-1) and granzyme B. The proliferation index, measured by Ki-67 expression was high with 60%." (PMID 33546043, 2021). "Similar to EATL, tumor cells in MEITL are typically CD3+, CD5−, CD7+, CD4−, TIA-1+, granzyme B+, perforin+, and CD103+." (PMID 34830926, 2021). "OS curves for the location of tumor infiltration of CD3+, CD8+, TIA1+ and CD20+ cells were also examined." (PMID 34885185, 2021). "Considering the infiltration sites in the tumor, we analyzed the CD3+, CD8+, TIA1+ and CD20+ cells regarding sex, age, tumor location and neoadjuvant chemotherapy." (PMID 34885185, 2021). "For example, the reduction in TIA-1 and TIAR has been shown to trigger cell proliferation and tumor growth and accelerate mitotic entry, respectively." (PMID 34095105, 2021). "Tumor cells typically exhibit a CD2+/−, cytoplasmic CD3+, CD4−, CD7+, CD8−, CD56+, CD103−, and TIA1+ phenotype." (PMID 34830926, 2021). "Two indolent TLPD patients demonstrated CD4+ T-cells in the tumor, and one ALCL patient had CD30+, CD4+ and TIA1+ tumor cells." (PMID 33087157, 2020). "Most RBPs (11 out of 16) act as oncogenes and only 5 (TIA1, TTP, QKI, ESRP1, CELF2, and QKI) present tumor suppressive abilities." (PMID 31440515, 2019). "TIA1 is a robust prognostic immunological biomarker in CRC and particularly in tumors with marked cytotoxic CD8+ tumor-infiltrating lymphocytes (TILs)." (PMID 31440515, 2019). "Tumour cells are CD3+, either CD4+ (more commonly) or CD8+, or in rare instances CD4−/CD8−, whilst those expressing CD8 have a cytotoxic profile (TIA1+, granzyme B±)." (PMID 30305106, 2018). "For example, TIA1 has been found to regulate VEGF isoform expression, angiogenesis, tumor growth and bevacizumab resistance in CRC." (PMID 28257633, 2017). "In this study, we demonstrated that TIA1 protein was significantly downregulated in CRC tissues and inhibited proliferation and migration of CRC cells and attenuated tumor growth in xenografted mice." (PMID 28257633, 2017). "In this study, we proved that miR-19a inhibits TIA1 to indirectly downregulate PDCD4, which is a TIA1 target as well as an important tumor suppressor in CRC." (PMID 28257633, 2017).
tumor (continued). "Our results suggest that TIA1 works as an ESCC oncogene and is likely to be a marker of malignant potential as well as a possible therapeutic target for this tumor type." (PMID 26958940, 2016). "Immunohistochemically, tumor cells are characterized by CD30, ALK, CD5, TIA-1, Granzyme B, EMA positive staining, and CD2, CD3, CD7, CD4, CD8, CD20, CD79a negative staining." (PMID 27612448, 2016). "Based on immunohistochemical staining, the phenotype of the tumor cells was CD3+, CD43+, CD56+, TIA-1+, CD30+, CD4-, CD5-, CD7-, CD8-, CD20- and CD79a-." (PMID 26126576, 2015). "Strikingly, strong TIA1 and TIAR staining was also detected in infiltrating inflammatory cells around the tumor regions, with a high proportion in lymphocytes, and also in adjacent non-tumor control cells (data not shown)." (PMID 25741594, 2015). "Knockdown of T-cell intracellular antigens TIA1 and TIAR in transformed cells triggers cell proliferation and tumor growth." (PMID 25741594, 2015). "This study provides the first characterization of TIA1 and TIAR tumor suppressor activity in cancer cells." (PMID 25741594, 2015). "Immunohistochemically, tumor cells showed CD3+, CD45RO+, CD5-, CD7-, CD4-, CD8-, CD10-, CD20-, CD30-, CD79a-, CD138-, CD56-, granzyme B-, TIA-1+ and ALK-." (PMID 22931631, 2012). "The pro-apoptotic CD14, TIA1, and ITGB2 were down-regulated in more than 50% of the tumor cultures after treatment with doxorubicin, as was the antiapoptotic YWHAH." (PMID 18959781, 2008). "Tumor tissue was examined by immunohistochemistry for expression of NY-ESO-1, various T cell markers (CD3, CD4, CD8, CD25, FoxP3, TIA-1 and Granzyme B) and other immunological markers (CD20, MHC class I and MHC class II)." (PMID 18923710, 2008). "Natural killer and cytotoxic cells (TiA1 or Granzyme B) tended to be more numerous in contact with residual tumour cells in the TAXHER01 tumours, with significant differences demonstrated for TiA1 (P<0.05) and NK1 staining (P<0.01)." (PMID 16404427, 2006). "Clinically, measuring TIA1 in tumor tissue may help identify patients more likely to benefit from BCG; for those with low TIA1, future strategies could consider metabolic or immune co-modulation to personalize treatment." (PMID 41300366, 2025). "As the therapies from tumor progression/regression inevitably vary, identification of key biomarkers such as circulating tumor DNA (ctDNA) concentrations, use of non-invasive biopsy for assessment of CD8+ and TIA1+ levels can aid therapy management." (PMID 40584631, 2025). "In addition, immunohistochemical analysis revealed that tumor cells were positive for CD3, CD43, CD56, TIA1, granzyme B, CD2, CD4, and CD7." (PMID 40433378, 2025). "The results showed that ASEs up-regulated in BLCA with high-level neoplasm grade were enriched to several RBPs’ motifs, including “poly-T” motifs and polypyrimidine tract (Py-tract) sequence of HuR, CPEB4, TIA1, HNRNPC, PTBP1, RALY and ZC3H14, and motifs of PCBP2 and SNRNP70." (PMID 37810965, 2023). "We found that expression of B7-H4 in tumor cells correlated positively with that of CD8 and TIA-1 and that in some tumors, the proportion of B7-H4-positive cells was correlated with the number of CD8-positive lymphocytes; this was particularly true in those cells with greater expression of PD-L1." (PMID 34275008, 2022). "Nevertheless, our data agree with a decreased TIA1 translation observed in HCC patients and other studies suggesting a tumor-suppressive function of TIA1 and a downregulation of its expression at the protein level in tumors, while the mRNA level remains unchanged." (PMID 35406476, 2022). "Although not considered a cancer-driver protein, TIA1 does have a role in tumorigenesis via its capacity to transcriptionally/post-transcriptionally regulate genes belonging to key pathways for tumor development." (PMID 35163320, 2022). "The tumor tissues express CD3ε, CD43, CD56, and cytotoxic molecules (such as TIA-1 and GB)." (PMID 33816224, 2021).